ACE (angiotensin I converting enzyme)
Diseases named in the same sentence as ACE in open-access papers (continued):
Sharing a sentence is not in itself a finding about the gene and the disease.
Obesity (continued). "There is some evidence to suggest the use of ACE inhibitors and ARBs as first-line agents in the obesity-linked primary hypertension population; in adults, these agents appear to reduce the incidence of new-onset diabetes and may increase insulin sensitivity." (PMID 39217385, 2024). "However, no previous studies have reported an association of the GNB3 and ACE gene polymorphisms with obesity in the PPCM population." (PMID 37089887, 2023). "Therefore, the association between ACE I/D polymorphism and obesity is plausible, as illustrated in several studies." (PMID 32408411, 2020). "Recent studies have demonstrated a probable association between ACE I/D polymorphism and obesity." (PMID 32408411, 2020). "Moreover, obesity is associated with an upregulation of angiotensin-converting enzyme (ACE) in adipocytes, and augmented levels of circulating angiotensin II (AngII)." (PMID 32373073, 2020). "From this perspective, the present study aimed to verify whether the AGT or ACE polymorphisms were associated with overweight and obesity in a population-based study in Brazil." (PMID 31365628, 2019). "Thus, the present study aimed to verify the possible association between angiotensinogen (AGT) or angiotensin-converting enzyme (ACE) polymorphisms with overweight and obesity in adults." (PMID 31365628, 2019). "Therefore, we performed a population-based study to verify the association between AGT and ACE polymorphisms with overweight/obesity in a general sample of Brazilian adults." (PMID 31365628, 2019). "This explains why VNTR and INDEL in eNOS and ACE, respectively, could be predisposing factors of obesity." (PMID 28615046, 2017). "We also suggest the inclusion of both males and females, but to be analyzed separately, to check whether ACE I/D polymorphism could justify the vast difference in obesity prevalence observed between Egyptian males and females." (PMID 27777603, 2016). "Based on our results, there is a trend in favor of the insignificant relationship between BMI and ACE gene I/D polymorphism, and this equivocal outcome may account for the different BMI cut-off points adopted by researchers to define overweight and obesity." (PMID 28115791, 2016). "In addition, we were able to determine correlations between individual miRNAs, miR-20a-5p, −22-5p, and −101-3p (p < 0.04), and the genetic predisposition for endurance and/or strength and obesity risk (ACE, ACTN3, and FTO), as well as between miRNAs and the body composition (p < 0.05)." (PMID 35937778, 2022). "Thus, this study aimed to investigate whether ACE I/D polymorphism influenced the susceptibly of developing obesity in Korean adults." (PMID 32408411, 2020). "While obesity has been strongly associated with increased insulin resistance and ACE being one of the factors associated with insulin resistance variants like ACE D allele may be expected to more significantly modulate T2DM risk in obese subjects." (PMID 26491214, 2015). "However, when the association was analyzed based on obesity status, we found significantly higher ACE DD genotype frequency in the hypertensive groups and an increased risk associated with it in the nonobese hypertensive group but not in the obese hypertensive group." (PMID 26491214, 2015). "Hence, obesity is wide associated with the overexpression of ACE." (PMID 23258993, 2012). "The heterogeneity of endpoints and therapies prevented stratification by treatment (ACE-i, SGLT2i, steroids/immunosuppressants) when assessing the effects of obesity." (PMID 41156559, 2025). "The expression of various genes was also causally associated with the risk of AD, confirming ACE and BIN1 as risk genes for AD, while a genetically predicted anti-obesity drug target gene CNR1 was a protective factor against AD risk." (PMID 40082927, 2025).
Obesity (continued). "Patients with obesity were more often treated with β-blockers, angiotensin-converting enzyme (ACE) inhibitors, or angiotensin II receptor blockers, diuretics, statins, and mineralocorticoid receptor antagonists at inclusion." (PMID 40737012, 2025). "Other factors that contributed to the reduction in the NT-proBNP levels included overweight, obesity, and ongoing treatment with cardioactive drugs, such as ACE inhibitors, spironolactone, B blockers, and diuretics." (PMID 40281858, 2025). "While prior research has reported that obesity attenuates the antihypertensive effects of ARBs and ACE inhibitors, our study provides quantitative insights into BMI-related differences in both blood pressure reduction and metabolic outcomes." (PMID 40255834, 2025). "In the univariable analysis, female sex, obesity, systolic blood pressure, statin, ACE inhibitors or ARBs, and beta-blockers intake were significantly related to a lower mortality." (PMID 39407904, 2024). "Obesity correlates with increased activity of angiotensin-converting enzyme (ACE) in white adipose tissue, which results in higher plasma concentrations of Ang-II and loss of its diurnal rhythm." (PMID 37189789, 2023). "The milk of camels, cows, and sheep has also been shown to contain antioxidant peptides, ACE inhibitors, anti-diabetic and anti-obesity peptides, and antimicrobial peptides." (PMID 36555744, 2022). "This suggests that HFD and obesity leads to increased tissue ACE activity in the coronary arteries, which increases the proteolytic degradation of bradykinin and thus attenuates its dilatory duration of action." (PMID 36421412, 2022). "Some studies indicate that rice residue protein has good biological functions, such as antioxidant activity, angiotensin-converting enzyme (ACE)-inhibitory activity, anti-hypertensive and anti-obesity activities." (PMID 36421096, 2022). "The milk-derived peptide Val-Pro-Pro was found to prevent a fatty inflammation response between fat cells and macrophages and to act as an ACE inhibitor to improve obesity-related insulin resistance, thereby improving the development of obesity." (PMID 36232527, 2022). "Obesity promotes increased plasma renin activity plasma angiotensinogen and angiotensin-converting enzyme (ACE) activity, promoting enhanced plasma levels of Ang II in obese patients." (PMID 33800427, 2021). "The relative risk analysis for of FTO, MC4R, ACE and MTHFR gene polymorphism with obesity and dyslipidaemia is performed independently in both the studied populations." (PMID 34414818, 2021). "Multiple studies have also reported a direct link between the ACE gene and obesity, and metabolic syndrome, due to increased adipocyte growth and function." (PMID 33507688, 2021). "Remarkably, in patients with obesity or metabolic syndrome, ACE inhibitors, the most used antihypertensive drug (49.2%), were continued without interruption and with no complications reported to date." (PMID 34803908, 2021). "A 12-week treatment of C57BL/6J mice, afflicted by diet-induced obesity, with an ACE inhibitor captopril increased peroxisome proliferator-activated receptor-g coactivator-1a, long-chain acyl-CoA dehydrogenase and HSL expression levels." (PMID 32781523, 2020). "The hyperactivated status of ACE/Ang II/AT1R axis is observed in metabolic diseases such as obesity, DM, and inflammation and in CVD." (PMID 33178033, 2020). "A peptide ValProPro derived from milk inhibited obesity-induced adipose tissue inflammation under the cascading effect of angiotensin-converting enzyme (ACE)." (PMID 30834248, 2019). "Angiotensin-converting enzyme (ACE) located on chromosome 17q23.3 has also been shown to have a potential role in obesity development." (PMID 30338250, 2018). "Individuals with obesity are often reported to have increased plasma renin and angiotensin converting enzyme (ACE) activities, plasma angiotensinogen (AGT), angiotensin II (ANG II), or aldosterone levels." (PMID 29540174, 2018).
Obesity (continued). "The difference in SBP and DBP between ACE inhibitor users and NoBPMed was significantly greater in those with obesity compared to normal weight (SBP: −15 ± 1 mmHg versus −7 ± 1 mmHg, P=0.002; DBP: −7 ±1 mmHg versus −2 ± 1 mmHg, P=0.002)." (PMID 30364090, 2018). "The ET-1 and the ACE inhibitions by tobacco, obesity and dyslipidemia are explained by the role of metabolic syndrome, generated by tobacco (mainly nicotine), complex lipids (among obese and dyslipidemic coronary patients)." (PMID 27894250, 2016). "In other rodent models of obesity, using either angiotensin-converting enzyme (ACE) inhibitors or AT1-specific antagonists increased drinking significantly with an associated decrease in food intake and body weight mainly through loss of fat." (PMID 27376070, 2016). "The obesity risk increased in the boys with the GRK4 A486V, ACE and SLC12A3 mutant and in girls with CYP11β-2 mutant and GRK4 A486V hetero type as they increased the residual-Na." (PMID 25768006, 2015). "The polymorphisms of ACE, SLC12A3 and CYP11β-2 showed a gender difference in the interaction of sodium intakes and obesity." (PMID 25768006, 2015). "Despite this body of knowledge linking the RAS with the adipose tissue and metabolism, the controversy remains regarding the real role of ACE activity in energy metabolism and obesity." (PMID 25926796, 2015). "The obesity risk increased 7.06, 16.8, and 46.09-fold more in boys with GRK4 A486V, ACE, and SLC12A3 mutants as sodium intake increased." (PMID 25768006, 2015). "Other candidate genes in association with T2DM include PPARγ, ACE (angiotensin converting enzyme), MTHFR (methylene tetrahydrofolate reductase), FABP2 (fatty acid binding protein-2), and FTO (fat mass and obesity associated gene)." (PMID 26587547, 2015). "The obesity risk increased with GRK4 A486V, ACE, and SLC12A3 variants in boys, whereas it increased with GRK4 A486V and CYP11B2 variants in girls as sodium intake increased." (PMID 25768006, 2015). "As expected, a 10-week high-fat diet led to obesity indicated by increased body and peritoneal adipose tissue weights, and ACE treatment significantly inhibited these pathological alterations." (PMID 26508977, 2015). "ACE inhibitors are also known to exhibit cardiovascular benefits and have been shown to improve vascular function in animal models of obesity." (PMID 23631400, 2013). "Differently from the systemic condition, in this obesity model an increase in cardiac ACE activity and gene expression was found, followed by higher levels of Ang II and AT2 receptor." (PMID 23077501, 2012). "Exercise training increases cardiac ACE2 activity and protein expression and prevents the increase in cardiac mass, cardiac ACE, Ang II, AT2 caused by obesity." (PMID 23077501, 2012). "In summary, the results of the present study showed that cardiac mass, cardiac ACE activity and gene expression, as well as Ang II concentration were increased, although systemic Ang II was decreased in a Zucker genetic model of obesity." (PMID 23077501, 2012). "Because ACE was identified as the most important predictor among all candidates, we checked for its relation with measures of obesity and other blood analytes." (PMID 21340022, 2011). "The relation between ACE and obesity has been suggested to lie in the local expression of the renin-angiotensin system and the possible trophic role of angiotensin II in the development of adipose tissue." (PMID 21340022, 2011). "Patients with a history of smoking, obesity, allergy, or use of ACE inhibitors should be questioned regarding cough and active clinical care pursued." (PMID 20003540, 2009). "The risk provided by obesity was found to be positively reinforced by AT1R CC in the whole population analysis and ACE I/D DD in all subgroups, particularly in females (SI = 2.82, SIM = 1.79; AP = 0.46) and ≥ 45 subgroup (SI = 4.13, SIM = 2.36, AP = 0.65)." (PMID 18637188, 2008).
Obesity (continued). "Obesity and hypercholesterolemia have been shown to play a role in ACE gene expression, but also in other RAS intervenients, such as AGT or AT1R." (PMID 18637188, 2008). "Another enzyme important in controlling obesity is the angiotensin-converting enzyme (ACE)." (PMID 40863620, 2025). "For example, the use of ACE-inhibiting oligopeptides have been reported in the management of several diseases, including cardiovascular disease, increased blood pressure, type 2 diabetes, and obesity." (PMID 41008949, 2025). "The Sobs, Chao1, and ACE indices of the obesity group were significantly lower than those of the control group (p < 0.05), indicating that microbial richness was markedly reduced in patients with obesity compared with that in healthy controls." (PMID 41211211, 2025). "Obesity is associated with RAAS overactivation, as demonstrated by increased adipose tissue MR expression and elevated plasma levels of aldosterone, renin, angiotensinogen, angiotensin-converting enzyme (ACE), and AT II." (PMID 35043013, 2022). "The findings suggest that it may be possible to use the ACE genotype to predict blood pressure response to childhood obesity from an early age." (PMID 34912641, 2021). "A careful history and physical examination might reveal that dyspnoea is because of obesity or cardiac disease, cough part of an upper airway cough syndrome or angiotensin-converting enzyme (ACE)-inhibitors and wheeze embedded in COPD or bronchiectasis." (PMID 33567835, 2021). "Serum ACE activity was found to be significantly higher in subjects with alcohol-use disorder compared with healthy controls, similar to the increases observed in patients with obesity." (PMID 34068824, 2021). "The protective effects against obesity, insulin resistance, and DM in trained animals were associated with lower AT1 receptor expression and ACE/ACE2 ratio, higher Mas receptor protein expression, and a shifted RAS balance toward the ACE2/Mas receptor axis in skeletal muscle." (PMID 33178033, 2020). "In conclusion, ACE I/D polymorphism has not been observed to be a powerful candidate gene for obesity in Korean adults." (PMID 32408411, 2020). "The link between LE and ACE expression levels and LE as an ACE inhibitor also provides a mechanism based upon which LE is not only useful in the management of obesity but could also be beneficial in the management of cardiovascular diseases." (PMID 32781523, 2020). "Angiotensin Converting Enzyme (ACE) expression and activity is associated with obesity." (PMID 32121233, 2020). "Diet-induced obesity in mice has been found to be reversed by ACE inhibitors." (PMID 32781523, 2020). "Global deletion of the ACE gene protects male mice against obesity-related metabolic complications." (PMID 31262355, 2019). "The frequencies of the D allele and the DD genotype of the ACE gene were higher in both groups pointing to an increased cardiovascular risk probably due to obesity and not T2DM." (PMID 29694640, 2018). "Although men with obesity have been shown to have elevated plasma concentrations of estrone sulfate compared to men without obesity, the superior blood pressure effects of ACE in obesity were only seen in women." (PMID 30364090, 2018). "We observed that women with obesity had bigger differences in blood pressure when using ACE inhibitors and ARBs than normal weight and overweight women which may be expected given the known physiology of ACE inhibitors and obesity." (PMID 30364090, 2018). "In conjunction with the superior blood pressure lowering effects in obesity with ACE inhibitors that we observed, the discordant antihypertension medication effects in those with obesity may have been masked in the ACCOMPLISH trial." (PMID 30364090, 2018). "Body fat and body weight could be raised and lowered accordingly by stimulating and inhibiting the production of Ang II, suggesting a possible link between ACE and obesity." (PMID 28115791, 2016).
Obesity (continued). "In this case the genetic augmentation of ACE activity triggers a phenotype of decreased body fat and mass under hyperlipidic diet, in opposition to other studies that point positive correlation between ACE activity and obesity." (PMID 25926796, 2015). "Furthermore, the results showed that EXT in the OZR prevented increase in CH, cardiac ACE activity, Ang II and AT2 receptor caused by obesity." (PMID 23077501, 2012). "Significant correlations between ACE and measures of obesity and other blood analytes." (PMID 21340022, 2011). "The adipokines with black lettering are those whose circulating levels are enhanced in obesity and whose total release by adipose tissue explants is enhanced in obesity: IL-6, IL-10, ACE, TGFβ1, ICAM-1, TNFα, IL-1β, PAI-1, and IL-8 that are released by nonfat cells." (PMID 20508843, 2010). "Pharmacotherapies targeting RAAS, including ACE inhibitors, angiotensin receptor blockers, mineralocorticoid receptor antagonists (MRAs) or renin inhibitors, may decrease high BP among patients with obesity." (PMID 40761303, 2025). "Thus, the data suggests that the ACE I/D polymorphism does not affect the risk of obesity in Korean adults." (PMID 32408411, 2020). "Moreover, the ACE II homozygosis was reported as predictor of extreme obesity and diabetes." (PMID 31365628, 2019). "Therefore, ACE inhibitor use may contribute to the obesity paradox, wherein CVD morbidity and mortality is lowered in those with obesity as a result of superior blood pressure reduction." (PMID 30364090, 2018). "ACE inhibitors and ARBs may be associated with more beneficial BP profiles in women with obesity, with no obesity-related BP differences for antihypertensive medication in men." (PMID 30364090, 2018). "Other perspectives hold that ACE genotypes were not linked to BMI and obesity." (PMID 28115791, 2016). "However, large samples of epidemiological studies that focus on the relationship of ACE gene I/D polymorphism and obesity are lacking." (PMID 28115791, 2016). "On the other hand, a clear effect of ACE I/D polymorphism on the association of obesity and insulin resistance could not be established." (PMID 27777603, 2016). "In addition, the antiproteinuric effect of ACE seems to be maximal in overweight/obese patients and less prominent in patients with normal BMI, suggesting role of glomerular hyperfiltration in pathogenesis of proteinuria in obesity." (PMID 26084279, 2015). "ACE inhibitors may be a promising therapeutic agent for obesity and its complications." (PMID 23894285, 2013). "Regarding the correlation analyses of RAS components with hepatic cytokines in individuals with obesity and MASLD, a significant positive correlation was observed between ACE, and all analyzed cytokines (TNF-α, IL-6, IL-4, IL-13, IL-10)." (PMID 39337863, 2024). "Our findings underscore the importance of Th2-mediated responses in regulating hepatic ACE levels, highlighting a potentially novel aspect of RAS modulation in patients with obesity and MASLD." (PMID 39337863, 2024). "The adipocyte expression of mRNA of renin, ACE-1, and AT1R was higher in adipocytes derived from individuals with obesity." (PMID 36973648, 2023). "Anion exchange chromatography was frequently used to isolate negatively-charged bioactive peptides, such as GNPWM, an anti-ACE peptide, EIAQDFKTDL, an anti-obesity peptide, and AGLQFPVGR, a hepatoprotective peptide." (PMID 36770900, 2023). "Other nominally significant associations were established between WHOCS scales and: IFNL4 rs12979860, ACEIs, obesity, ARA-II, HCP5 rs2395029, ACE rs1799752, DPP4 rs17574, HMOX1 rs2071746, IL10 rs1800896, IL6 rs1818879, NFKB1 rs28362491, and MX1 rs469390." (PMID 35636966, 2022). "Accordingly, obesity is also characterised by high levels of AGT and angiotensin-converting enzyme (ACE) —two fundamental components of the renin-angiotensin system (RAS)—which plays a central role in the regulation of blood pressure and energy homeostasis." (PMID 35628332, 2022).